BRCA1 (BRCA1 DNA repair associated)
Diseases named in the same sentence as BRCA1 in open-access papers (continued):
Sharing a sentence is not in itself a finding about the gene and the disease.
breast cancer (continued). "Since then, treatment of breast cancer has evolved and survival increased, maybe allowing the detection of a previously hidden link between mutation of BRCA1 and the risk to develop GBM." (PMID 25880076, 2015). "Our results may account for their observation that BRCA1-associated breast cancers more frequently had a posterior location because BRCA1 mutation carriers have a greater tendency to have triple-negative cancers." (PMID 25608004, 2015). "While interplay between BRCA1 and AURKA-RHAMM-TPX2-TUBG1 regulates mammary epithelial polarization, common genetic variation in HMMR (gene product RHAMM) may be associated with risk of breast cancer in BRCA1 mutation carriers." (PMID 25830658, 2015). "This frequency is comparable with the mutation frequency of BRCA1 (∼2%) in breast cancers." (PMID 26136358, 2015). "Therefore, we sought to determine the importance of loss of BECN1 and of BRCA1 expression in women with ER-negative subtypes of breast cancer." (PMID 25825707, 2015). "In case of BRCA1 associated breast cancers, TRs might display excellent targets for novel drugs, especially in triple-negative cases." (PMID 26029931, 2015). "In contrast, LOH of the BRCA1 gene is frequently reported in BRCA1-mutated breast cancers." (PMID 26553136, 2015). "However, in our previous work, an even smaller number of BRCA1-mutated basal-like breast cancers proved sufficient to identify BRCA1-associated CNAs." (PMID 26553136, 2015). "In addition to these screens, the breast cancer susceptibility genes, BRCA1 and BRCA2, have recently been shown to regular IGF-1R expression or influence the downstream signaling." (PMID 26217584, 2015). "In this study, we investigated the antiproliferative effects and mechanism of PARP inhibitors ABT-888 (Veliparib), BSI-201 (Iniparib) and AZD228 (Olaparib) in breast cancer cell lines with BRCA1 or BRCA2 mutations and 9 different BRCA wild-type cell lines with BRCA1 allelic loss." (PMID 25975349, 2015). "This latter finding may explain in part the rapid onset of breast cancer development in individuals with BRCA1 mutations." (PMID 26106036, 2015). "The study also showed that addition of hydrocortisone, which binds the GR, eliminates the interaction between GR and GABPβ, causing a deficiency of the GABP transcription factor to the BRCA1 gene, which decreases its expression, and increases the risk of breast cancer." (PMID 26442220, 2015). "Moreover, luminal progenitors are thought to be at the origin of the triple-negative, basal-like, Brca1-associated breast cancers, indicating that they display phenotypic plasticity and an ability to upregulate basal markers." (PMID 26165517, 2015). "These BRCA1/2-associated breast carcinomas account for 5-7% of all breast cancer cases." (PMID 26378051, 2015). "In order to potentially act on available risk-reducing and breast cancer management options, it is necessary to first identify women who may be at increased risk for breast cancer owing to family history, BRCA1/2 mutations, and other factors." (PMID 27417765, 2015). "Indeed, women bearing pathogenic germline BRCA1 mutations have a 45% to 80% risk to develop breast cancer by age 70, and 36% to 66% for ovarian cancer." (PMID 25880076, 2015). "Approximately 70–80% of BRCA1-associated breast cancer cases are ER-negative." (PMID 26221963, 2015). "Moreover, loss of BRCA1 heterozygosity in humans with germline BRCA1 mutations is necessary for the development of BRCA1 mutant-associated breast cancers." (PMID 25825707, 2015). "An interaction between rs299290 and rs6064391 (in intron 2 of CSTF1) could reduce breast cancer risk in both BRCA1 and BRCA2 mutation carriers (interaction HRs = 0.87 and 0.73, respectively)." (PMID 25830658, 2015). "BRCA1 has long been known to be associated with breast cancer and ovarian cancer." (PMID 26485712, 2015).
breast cancer (continued). "CNVs have been reported to encompass genes known to be involved in breast cancer susceptibility, including BRCA1 and BRCA2, and therefore may similarly affect other genes involved in breast cancer-related pathways." (PMID 27600231, 2015). "Intriguingly, mounting evidence indicated that breast cancers with BRCA1 mutation were more likely to exhibit triple-negative phenotype compared with the BRCA1 noncarriers, which showed that BRCA1 could play a unique role in the progression of TNBCs." (PMID 25695063, 2015). "Two recurrent mutations were separately detected in two unrelated breast cancer patients in our study, and we have previously reported that the BRCA1 c.5468-1_5474del8 mutation, together with another recurrent mutation, 1100delAT, accounted for 34.8% of all BRCA1 mutations." (PMID 25927356, 2015). "Also BRCA1 mutated and basal-like breast cancer cells were found to be sensitive to oxidative DNA damage induced by H2O2 treatment." (PMID 26267318, 2015). "The BRCA1/2 mutated patients belong to a group that already contains a high number of triple negative and basal-like breast cancers, but here we showed that triple negative tumors in BRCA1/2 mutated carriers are even more highly expressing ANXA1 than triple negative patients in the BCAC cohort." (PMID 26137966, 2015). "For BRCA1 mutated breast cancers, specific CNAs are reported." (PMID 26553136, 2015). "Although we were careful not to recruit familial cases for our study it is interesting to note that in Uruguay there is a predominance of BRCA2 over BRCA1 mutations in breast cancer families, which may be linked to their ethnic origin." (PMID 25783644, 2015). "Furthermore, it has been established that patients with BRCA1 mutations are more likely to develop basal like breast cancers (including the triple negative molecular subtype)." (PMID 26010605, 2015). "Interestingly, overall survival rate of patients carrying a BRCA1 germline mutation was significantly higher than in sporadic breast cancer cases (p < 0.001)." (PMID 26029931, 2015). "BRCA1-associated breast cancers have been shown to be more likely ER-negative for each age group (<45, 45–54, and 55–64 years), with an increase in ER-positive breast cancers with increasing age." (PMID 26221963, 2015). "Currently the major genes known to influence breast cancer risk is BRCA1 and BRCA2." (PMID 26010605, 2015). "Moreover, an ongoing phase II (NCT01078662) study of olaparib monotherapy in BRCA1/2 mutation carriers of different tumour types revealed clinical benefit in prostate and pancreatic cancer as well as activity in ovarian and breast cancer." (PMID 26610585, 2015). "A significant event leading to the development of breast cancer is loss of BRCA1 function." (PMID 26442220, 2015). "TNBC and basal-like breast cancer show considerable overlap with BRCA1 mutated tumors." (PMID 26387133, 2015). "The potential role of FAK in BRCA-related breast tumors still remains less investigated although BRCA1 has been described to be implicated in the invasion of breast cancer cells by controlling the turnover of specific receptors involved in focal adhesion, cell-cell and cell-matrix contacts." (PMID 25333258, 2015). "BRCA1 is a susceptibility gene that has a genetic predisposition for breast cancer." (PMID 25789047, 2015). "Indeed, substantial heterogeneity of causative alleles at a single disease locus is not uncommon even for monogenic subtypes of human diseases, including breast cancer due to BRCA1 mutations." (PMID 26161957, 2015).
breast cancer (continued). "In vitro studies of BRCA1-related breast cancers appear to be particularly susceptible to platinum-based drugs chemotherapy, which could be relevant by extrapolation to the treatment of TNBCs." (PMID 26196284, 2015). "Detection of BRCA1/2 variants in fixed tissue is feasible, and could be performed prospectively to facilitate optimum treatment decisions for ovarian or breast cancer patients." (PMID 25859162, 2015). "Interestingly, several miRNAs that were up-regulated in sporadic breast carcinomas were also up-regulated in BRCA1-associated breast carcinomas from our analysis compared to normal breast tissues from BRCA1 germ-line mutation carriers." (PMID 26378051, 2015). "Little is known about miRNA expression in BRCA1/2-associated breast carcinomas." (PMID 26378051, 2015). "We found no clear indications whether miRNA deregulation in BRCA1/2-associated breast carcinomas could be due to direct effects of impaired BRCA1/2 function." (PMID 26378051, 2015). "Moreover, several miRNAs were deregulated in the opposite direction between BRCA1/2-associated breast carcinomas and sporadic breast carcinomas." (PMID 26378051, 2015). "Indeed, about 21% of deregulated miRNAs matched reported locations of chromosomal instability in BRCA1/2-associated breast carcinomas and fragile sites in the genome." (PMID 26378051, 2015). "This may be due to the extensive chromosomal instability seen in BRCA1/2-associated breast carcinomas, leading to loss of chromosomal regions and consequently, miRNA genes." (PMID 26378051, 2015). "Considering the proven existence of an inversely correlation between breastfeeding duration and breast cancer risk, an important case-control study, examined the relationship between breast-feeding and breast cancer risk among women who carried deleterious mutations in the BRCA1 or BRCA2 gene." (PMID 24763114, 2014). "Furthermore, a subgroup of TNBCs also shares the characteristic genomic pattern of specific CNAs associated with BRCA1-mutated breast cancer." (PMID 25083859, 2014). "As well as its role in DNA repair and breast cancer susceptibility, BRCA1 has also been implicated in mammary stem-cell self-renewal (reviewed), with deletion of BRCA1 during epidermal development showing that it is required for the development of adult hair follicle stem cells." (PMID 25519510, 2014). "In order to test whether the BRCA1-mutation DNAme signature is able to identify women who will develop breast cancer we analysed one of the best available characterised longitudinal cohorts." (PMID 25067956, 2014). "This is best evidenced by determining the BRCA1 germline mutations as genetic predispositions in breast cancer, in which the definitive conclusion for its contribution to breast cancer is based on the mouse models showing development of breast cancer with the germline mutated BRCA1." (PMID 24969172, 2014). "BRCA1+ is the strongest germline predisposition for familial breast cancer." (PMID 24884718, 2014). "Given their important role in breast cancer predisposition, it is timely that genetic testing include the evaluation of mutations in these additional 23 genes, and not only mutations in BRCA1 and BRCA2, which represents the current testing protocol in cancer genetic clinics." (PMID 24667084, 2014). "In line with this, clinicopathological data indicated that hypermethylation of the -132 site may be an effective indicator for histological grade and estrogen receptor status in BRCA1-mutated breast cancer tissues." (PMID 24675476, 2014). "The median age of breast cancer diagnosis in carriers of the c.190T>C mutation (39.7 years) was similar to that observed in 425 breast cancer patients with other pathogenic BRCA1 mutations ascertained at the institutions participating in this study (40.1 years)." (PMID 24516540, 2014).
breast cancer (continued). "These BRCA1 expression-metabolite associations are entirely consistent with in vitro mechanistic studies implicating BRCA1 in these processes and as such, constitute direct support for the physiologic relevance of these pathway connections in breast cancer." (PMID 25091696, 2014). "Two overlapping subtypes, triple negative (TN) breast cancer lacking estrogen receptor (ER), progesterone receptor (PR), and Her2 receptors, and basal-like breast cancer, which is generally associated with BRCA1 activation, are normally more aggressive and have poorer prognoses." (PMID 25309874, 2014). "Overall, deleterious BRCA1/2 mutations were detected in 21/726 (2.9%) breast cancer cases." (PMID 24944648, 2014). "In addition, carrying BRCA1/BRCA2 germline mutations has been associated with a high risk of contralateral breast cancer." (PMID 24834114, 2014). "The main aim of the present study was to investigate, at the molecular level, whether women with methylated BRCA1 promoter in their WBC are indeed at an elevated risk of developing breast cancer." (PMID 25403427, 2014). "Another important player in the controlling the breast cancer development is BRCA1 (breast cancer type 1 susceptibility protein), which is the 1863 amino acids protein with an amino terminal zinc ring finger motif, two nuclear localization signals, and two C-terminally located BRCT domains." (PMID 25988147, 2014). "Importantly, the BRCA1-mutation DNAme signature also substantially overlapped with an ER + breast cancer specific risk signature, which we derived de novo in the UKCTOCS cohort (P <2 x 10-33)." (PMID 25067956, 2014). "The presence of methylated BRCA1 promoter in healthy females may reveal predisposition of these individuals to develop breast cancer." (PMID 25403427, 2014). "Moreover, the evolutionary dynamics of BRCA1-mutated breast cancer initiation were also considered, with the assumption that the number of cells is constant." (PMID 25158060, 2014). "We evaluated whether differences in associations of known breast cancer susceptibility variants between BRCA1 carriers, BRCA2 carriers and the general population are mediated by tumor ER status in mutation carriers." (PMID 25919761, 2014). "Here we tested the hypothesis that women with an extremely high breast cancer risk (due to a BRCA1 mutation) carry a specific methylation signature in peripheral blood cells, which is also able to predict sporadic breast cancer incidence and death." (PMID 25067956, 2014). "In addition, we analyzed the correlation between total transcript levels or transcript 1 levels, and the number of methylated sites at -132 site or around the PEMT core promoter region (−529 to +239) in BRCA1-mutated breast cancer and normal breast tissues." (PMID 24675476, 2014). "This may help to explain why global DNA methylation was further reduced in BRCA1-mutated breast cancer." (PMID 24675476, 2014). "Interestingly, apart from the number of nodes, none of the other clinico-pathological features or treatment modalities was associated with the BRCA1-mutation DNAme signature in these ER positive breast cancers." (PMID 25067956, 2014). "Interestingly, for BRCA1 mutation carriers, certain morphological subtypes of breast cancer, most frequently medullary carcinoma, as well as higher grade tumors, were reported to occur more commonly than in the sporadic counterparts." (PMID 24959366, 2014). "A cohort of familial breast cancer patients (N = 57), at risk individuals (N = 25) and healthy controls (N = 23) were analyzed using multiplex ligation-dependent probe amplification method to detect BRCA1 and BRCA2 large genomic rearrangements." (PMID 24906410, 2014).
breast cancer (continued). "However, BRCA1 open-reading-frame variants only account for a small portion of hereditary breast cancer cases that occur primarily in young, premenopausal patients." (PMID 24915755, 2014). "In this study, we report for the first time that (i) BRCA1-mutated breast cancer displayed a hypermethylated E2F1 motif and promoter region; (ii) the hypermethylated E2F1 motif was negatively correlated with DNMT1 mRNA levels; and (iii) E2F1 is a key transcriptional regulator of DNMT1." (PMID 24502362, 2014). "The search for high-susceptibility genes that can explain the breast cancer risk in the remaining non-BRCA1/2 families is complicated by their underlying genetic heterogeneity, and a probable explanation of the low success rate of attempts to identify new high-risk alleles." (PMID 24479546, 2014). "However, several breast cancer susceptibility genes identified so far, such as BRCA1 and BRCA2, account for only less than 5% of the total breast cancer incidence." (PMID 25559835, 2014). "Indeed, PSC in many ways can mimic epithelioid mesothelioma, but unlike mesothelioma, PSC is linked to hereditary and sporadic mutations of two breast cancer susceptibility genes (BRCA-1 and BRCA-2)." (PMID 24910640, 2014). "Although they had been selected based on their evidence of association with breast cancer risk, under the initial hypothesis they are also plausible modifiers of ovarian cancer risk for BRCA1 and BRCA2 mutation carriers." (PMID 24698998, 2014). "The BRCA1-mutation DNAme signature predicted the development of an ER positive breast cancer with an AUC = 0.57 (0.50 to 0.64; P = 0.03) independent of whether the sample was taken less or more than 2 years prior to diagnosis." (PMID 25067956, 2014). "Prior studies have questioned the importance of mammographic density for breast cancer risk prediction among BRCA1/2 mutation carriers; further research is warranted to investigate the predictive value of computer-extracted texture features among this high-risk patient population." (PMID 25159706, 2014). "Breast cancers with a BRCA1 mutation are also frequently triple-negative and basal-like." (PMID 24507701, 2014). "Another hallmark of the molecular basis of breast cancer is the loss of function of BRCA1." (PMID 24460909, 2014). "It is believed that BRCA1+ leads to breast cancer by causing genome instability." (PMID 24884718, 2014). "Accordingly, specific regulatory mechanisms may exist, and DNMT1 expression is likely to be the result of a complex interaction of multiple factors in BRCA1-mutated breast cancer cells." (PMID 24502362, 2014). "Importantly the BRCA1-mutation DNAme signature was able to predict breast cancer mortality (AUC = 0.67; 95% CI 0.51 to 0.83; P = 0.02)." (PMID 25067956, 2014). "In addition, these authors predicted that approximately two in nine women with TN breast cancer and additional high-risk features (early onset or family history) harbor a BRCA1 mutation." (PMID 25857409, 2014). "Of all women with breast cancer, 5 to 10% may have a germline mutation of the genes BRCA1 and BRCA2." (PMID 25184114, 2014). "Inherited mutations in BRCA1 or BRCA2 increase the risk of breast cancer in women by around 56–84%." (PMID 25293656, 2014). "Detecting BRCA1/2 mutations is a generally accepted strategy for predicting early breast cancer." (PMID 25437005, 2014).